IL2 (interleukin 2)
Diseases named in the same sentence as IL2 in open-access papers (continued):
Sharing a sentence is not in itself a finding about the gene and the disease.
cancer (continued). "IL-2 also stimulates T cells to proliferate, contributing to immune tolerance and cancer progression." (PMID 41376630, 2025). "IL-2, the first member identified in this family, has been thoroughly studied for its role in cancer." (PMID 40636453, 2025). "A phase I/II study treated 10 patients with cancer with an autologous DC vaccine pulsed with tumor lysate and keyhole limpet hemocyanin+ IL-2." (PMID 40303301, 2025). "We demonstrate that timed IL-2R subunit-biased IL-2 immunotherapy synergizes with single high-dose RT to achieve potent anti-cancer immunity." (PMID 40502703, 2025). "The mechanism of systemic IL2 therapy in cancer immunotherapy includes the stimulation of lymphoid proliferation in tissues and the activation of host-derived T cells in vivo." (PMID 41050655, 2025). "The curative effect of IL2 in cancer treatment is dose-dependent, and HD IL2 was always necessary to achieve clinical efficacy." (PMID 41050655, 2025). "In denileukin diftitox, the bacterium’s toxin was also modified to contain interleukin-2 (IL-2), which targets the IL-2 receptor on the surface of IL-2-expressing cells, such as certain cancer cells." (PMID 40519767, 2025). "IL-2 has a promising future in immunotherapy, particularly for cancer, autoimmune and infectious disease." (PMID 41376630, 2025). "Immunotherapeutic modalities—including checkpoint inhibitors (PD-1/PD-L1, CTLA-4), CAR-T and CAR-NK cell therapies, cytokine-based treatments (e.g., IL-2, TNF-α), cancer vaccines, and oncolytic viruses—are all susceptible to immune remodeling induced by μg." (PMID 40940834, 2025). "IL-2 promotes T cell proliferation and activation, and high-dose IL-2 has shown the capacity to elicit potent immune responses against cancer cells." (PMID 40649958, 2025). "IL‐2 is the first immunotherapy to receive approval for cancer treatment, and a total of 36 IL‐2‐based compounds have entered clinical trials for oncology, with most of these agents still in the early stages of evaluation." (PMID 40959206, 2025). "Liposomal formulations of IL-2 have demonstrated significant promise for cancer therapy in preclinical studies, providing enhanced biodistribution, improved therapeutic efficacy, and reduced toxicity." (PMID 40143046, 2025). "Human studies were, therefore, conducted in patients with several inflammatory bowel diseases and cancers, demonstrating the ability of labeled IL2 to quantify the presence of CD25+ cells (IL2R) and to monitor therapeutic efficacy." (PMID 40869484, 2025). "Interleukin-2 (IL-2) based immunotherapy has been approved for treating certain types of cancer, as IL-2 plays a crucial role in regulating the immune system." (PMID 40670434, 2025). "IL-2, IL-12, and TNFα are potent pro-inflammatory cytokines that have been identified as promising anti-cancer biopharmaceuticals." (PMID 39773310, 2025). "A circRNA–based IL-2 therapy features prolonged IL-2 half-life, low Treg activation, and high safety for cancer immunotherapy." (PMID 40009662, 2025). "Recently, cytokines like IL2, IL‐7, IL‐10, and IL‐12 have been tested in clinical trials for the therapy of certain cancers (reviewed elsewhere)." (PMID 38813869, 2025). "IFN-γ and IL-2 are essential in the immune response against cancer by enhancing the cytotoxic activity of immune cells such as T cells and NK cells." (PMID 41583493, 2025). "IL-2 therapy works by augmenting the immune response to cancer, activating and inducing effector CD8+ T-cell and NK-cell proliferation." (PMID 38339310, 2024). "The IPCGOR combined with IL-2 regimen not only shows promising clinical benefits but also positively influences patients' lived experiences during their cancer journey." (PMID 38434976, 2024). "Pathway enrichment using Hallmark gene sets (MSigDB) revealed enrichment of key cancer hallmarks such as epithelial-to-mesenchymal transition (EMT), IL-2 STAT5 signaling, and early response to estrogen." (PMID 39171293, 2024).
cancer (continued). "The synergy of PD-L1 targeting and IL-2 immunostimulation presents a promising strategy for cancer immunotherapy, marking a significant breakthrough in oncology." (PMID 38834889, 2024). "Cancer cells from solid tumors lack the expression of IL-2R, signifying that the therapeutic impact of administered IL-2 can be primarily attributed to its immunological effects that promote the cytolytic activity of both NK and CD8+ cell types." (PMID 39204319, 2024). "Given the limitations of cancer monotherapy using IL-2, studies have been conducted on the use of IL-2 in combined immunotherapies with cytokines such as IFN-α with LAK cells and T cells, classical anticancer drugs and immune checkpoint inhibitors." (PMID 38539570, 2024). "We focused on the IL-2 pathway given its therapeutic relevance in both cancer and autoimmunity and increasing interest in IL-2 mimetics." (PMID 38245524, 2024). "Retinoids increase the number of receptors for interleukin-2 (IL-2), which is responsible for mobilizing the immune system in the fight against cancer." (PMID 38732639, 2024). "High doses of IL-2 have been approved for conventional adoptive cell therapy (ACT) in cancer treatment for promoting the development and activity of all T cell subsets, including regulatory T (Treg) cells which dampen immune responses against tumors." (PMID 38769543, 2024). "Second, limiting Treg infiltration into the TME prevented CD8+ TILs from gaining TOX and functional exhaustion in an IL-2–dependent manner, leading to effective eradication of cancer." (PMID 38787791, 2024). "Collectively, these data support the therapeutic potential of CD8+ T cell–selective IL2 for the treatment of cancer." (PMID 38563906, 2024). "CD3 agonistic antibodies and low-dose IL-2 are frequently employed as tools to expand T cells in a multitude of clinical applications, including adoptive T cell therapy for cancer patients." (PMID 39737308, 2024). "Recombinant IFNα and IL-2 are the only cytokines that have been approved in the United States for the treatment of cancer, even though their efficacy was modest." (PMID 39697343, 2024). "Tucotuzumab celmoleukin (huKS-IL2), an immunocytokine that acts by genetically fusing interleukin-2 (IL-2) to a humanized monoclonal antibody against EpCAM, has demonstrated safety and immunologic activity in cancer patients." (PMID 39595576, 2024). "In conclusion, our findings dissect the underlying mechanisms by which PGE2 inhibits IL-2 signalling and, as a result, human TIL proliferation, with important clinical implications for improving TIL-ACT and cancer immunotherapy." (PMID 38658764, 2024). "The efficacy of the ACT in treating cancers depends on the engineered cell production of a wide variety of cytokines, including interleukin-IL-2 (IL-2), IL-4, IL-6, TGF-β, interferon-γ, tumor necrosis factor-α (TNF), IL-8, and IL-10, IL-15, IL-18, IL-21, etc.." (PMID 39105847, 2024). "In the field of cancer therapy, IL-2 has been used for the activation of lymphokine-activated killer cells (LAK)." (PMID 38893211, 2024). "A novel approach based on Vγ9Vδ2 T-cell stimulation using an agonistic BTN3A-specific monoclonal antibody alone or in combination with IL-2 is currently being evaluated in a phase 2 clinical trial in advanced-stage cancer patients." (PMID 39493452, 2024). "Subsequently, these isolated TILs are stimulated with interleukin-2 (IL-2) and reintroduced into the patient through infusion, aiming to target and attack the cancer cells." (PMID 38474400, 2024). "This study showed the potential of recombinant cytokines as therapeutics for cancer and the approval of recombinant IL-2 (Proleukin) for metastatic renal cancer quickly followed." (PMID 39204319, 2024). "Interleukin-2 is crucial for combating cancer, but its use is restricted due to severe side effects." (PMID 39218982, 2024). "CD4 + Th1 cells, stimulated by IL-12, IFN-γ, and IL-2, secrete pro-inflammatory cytokines, and have anti-cancer effects." (PMID 37505298, 2024).
cancer (continued). "As an alternative, many groups have used NK-92 cells, an interleukin-2 (IL-2) -dependant human NK cell line, that can be easily expanded, engineered, and has demonstrated sustainable cytotoxicity against many cancer types." (PMID 38722382, 2024). "This review focuses on ICKs designed with the most impactful cytokines in the cancer field: IL-2, TNFα, IL-10, IL-12, IL-15, IL-21, IFNγ, GM-CSF, and IFNα." (PMID 39204319, 2024). "Their use in cancer immunotherapy dates back to the 1970s with successful applications like IL-2 for advanced melanoma." (PMID 39040921, 2024). "In light of these observations, some studies have investigated eosinophils in cancer immunotherapies, finding that stimulation with IL-2 resulted in increased levels of eosinophils and their cytotoxicity on cancer cells." (PMID 39766202, 2024). "Such as interleukin-2 (IL-2), one of the prototypical examples of successful cytokine-based immunotherapy for cancers, has been studied for over 47 years." (PMID 38753073, 2024). "IL-2, a type I cytokine, is the earliest approved for cancer therapy because of its significant and long-lasting efficacy, but the high toxicity of IL-2 at high-dose administration limits its use." (PMID 38762484, 2024). "IL‐2 has been considered a proinflammation factor and has played an essential role in malignant tumors since it was discovered." (PMID 38270322, 2024). "The effects of HD IL-2 on the thymus were first assessed in vivo, given its relevance as a cancer immune therapy." (PMID 39315105, 2024). "TNFα and IL-2 are incorporated into OAds to selectively infect cancer cells through tumor-specific promoters and knob protein exchange, thereby enhancing cancer cell entry." (PMID 39055561, 2024). "The ex vivo expansion and reinfusion of TILs have been effectively implemented for treating various cancers, usually involving IL-2 for TIL expansion and subsequent support of these cells after reinfusion." (PMID 39727496, 2024). "IL-2 is a cytokine used in immunotherapy for the treatment of ccRCC through its ability to activate cancer cell-specific immune cells, representing another example of valuable treatment alongside the ICIs." (PMID 38893211, 2024). "This review explores the historical context of IL-2 as an immunotherapeutic agent and discusses future directions for its use in cancer immunotherapy." (PMID 39218982, 2024). "IL-2 therapy aims to stimulate the proliferation and activation of T cells, boosting their ability to recognize and attack cancer cells." (PMID 39015563, 2024). "Interleukin-2 (IL-2) is one of the first cytokines to be discovered as an immune agonist for cancer immunotherapy." (PMID 38638426, 2024). "In this review we discuss the biological characteristics of IL-2 and its receptors, as well as its efficacy and treatment limiting toxicities in cancer patients." (PMID 39114660, 2024). "By promoting the expansion and activation of cytotoxic T cells and NK cells, IL-2 facilitates the recognition and elimination of cancer cells." (PMID 39169031, 2024). "IL-2 is an extremely important cytokine from the perspective of cancer immunotherapy, due to its pleiotropic action on the immune system." (PMID 38539570, 2024). "IL-2 stimulates the proliferation of activated lymphocytes, enhancing the body's capacity to identify and combat cancer cells 19-20." (PMID 38434976, 2024). "Previous studies have shown that due to the short serum half-life, the administration of higher doses of IL-2 will be required for efficient antitumor activity, which will lead to unacceptable toxicity in treated cancer patients." (PMID 38337114, 2024). "These properties make IL‐2‐Fc a versatile and unique antitumor agent that is worth pursuing for clinical use in multiple cancer indications." (PMID 38317590, 2024). "PD-L1 on cancer cells affected the activation of Jurkat T cells by binding to the PD-1 receptor on activated T cells, resulting in decreased IL-2 expression." (PMID 39811730, 2024).
cancer (continued). "The FDA has approved 16 immunomodulators for treating different types of cancer, with IL-2 being an extensively researched cytokine." (PMID 38655260, 2024). "High-dose (HD) IL2 was the first immunotherapy to show complete responses in a subset of patients with cancer, and recent studies support the continuing utility of IL2 in the modern era." (PMID 38563906, 2024). "This study identifies the PGE2–EP2/EP4 axis as a molecular target to restore IL-2 responsiveness in anticancer TILs to achieve cancer immune control." (PMID 38658748, 2024). "This necessitates high-dose IL-2 injections in anti-cancer treatments, but the activation of effector T cells coincides with the activation of immunosuppressive Tregs." (PMID 38352877, 2024). "For this reason, research groups are working to improve the performance of this therapeutic strategy, targeting genes encoding immune checkpoint proteins, e.g., PD1, or suppressing IL-2 in mouse cancer models." (PMID 39727987, 2024). "High dosages of IL-2 have been approved for cancer treatment, primarily because when the concentration is low, the majority of IL-2 likely binds to the IL-2Rα:IL-2Rβ:γc complex." (PMID 39169031, 2024). "And in a retrospective analysis of cancer patient data, a high IL-2 pathway signature strongly correlated with response rates to PD-1 blockade." (PMID 39114660, 2024). "IL-2 is a crucial T-cell cytokine that promotes T-cell proliferation and effector function, and is considered as an effective immunotherapy treatment for cancer." (PMID 39772010, 2024). "PD-1 blockade promotes a Th1/Th17 response via enhanced production of interferon γ, interleukin (IL)-2, tumor necrosis factor-α, IL-6, and IL-17 and reduction of Th2 cytokine profiles in patients with cancer." (PMID 39823053, 2024). "Cytokine such as IL-2 provides robust stimulation on NK cells, but IL-2 also activates suppressive T regulatory cells (Treg) which in turn impede NK cells to eliminate cancer cells." (PMID 38726000, 2024). "Interleukin-2 (IL-2), a cytokine with pleiotropic immune effects, was the first approved cancer immunotherapy agent." (PMID 38834889, 2024). "Immunotherapy has improved treatment outcomes for cancer patients, and ongoing efforts include a focus on harnessing the therapeutic potential of cytokines such as IL-2 and IL-15 in various cancer indications." (PMID 38887559, 2024). "Beyond IL-2 and IL-12, GM-CSF is another well-studied cytokine adjuvant with potential for incorporation into EV-based cancer immunotherapy." (PMID 39040921, 2024). "The CD3+CD56+ subset of cytokine-induced killer (CIK) cells, which are developed from blood and cultured with recombinant IL-2, was considered more effective against tumors due to its enhanced ability to target and destroy cancer cells." (PMID 39727496, 2024). "Cytokine therapy remains a key research interest in cancer therapy, with an IFNα (Peginterferon-α 2b) and IL-2 (Aldesleukin) therapies approved for specific cancers." (PMID 39411713, 2024). "This section provides an overview of the recent advancements and potential implications of combinatorial approaches in unlocking the full therapeutic potential of IL-2 for cancer treatment." (PMID 39114660, 2024). "The approval of cytokine therapies such as IFN-α and IL-2 for the treatment of certain cancers has been a testament to the clinical potential of targeting cytokine pathways." (PMID 39034318, 2024). "Nevertheless, only a small fraction of cancer patients respond to ICIs, and research on IL-2 as a combination treatment to improve the efficacy of these ICIs is ongoing." (PMID 39218982, 2024). "This means that these immunocytokines that specifically target cancer cells have a wider therapeutic window than unconjugated IL-2." (PMID 38337114, 2024). "IL‐2 plays a crucial role in stimulating the immune system, which has the potential to eliminate cancer." (PMID 38647237, 2024).
cancer (continued). "IL-15, like IL-2, holds great potential for boosting NK cell function and enhancing the immune response against cancer." (PMID 38545115, 2024). "IL-2 was identified as an early potent immunotherapeutic agent against cancer, demonstrating different affinities to various receptors." (PMID 38352877, 2024). "The pivotal role of IL-2 and IL-2R in this immunological response underscores their significance in the advancement of cancer treatment modalities." (PMID 37516849, 2023). "When IL-2 is used for cancer therapy, it is manufactured into a product called aldesleukin; a drug used to boost the immune system to fight cancer cells." (PMID 38001643, 2023). "The first use of cytokines in cancer treatment occurred in 1976, following the discovery of interleukin-2 (IL-2), initially known as a T-cell growth factor, which appeared to have the capacity to activate T cells and thus exert immune-stimulatory properties." (PMID 37345057, 2023). "Our understanding of the IL-2 and IL-2R pathways within the context of cancer has significantly evolved, opening avenues for improved and safer therapeutic interventions." (PMID 37516849, 2023). "Although preclinical models have shown promise, the efficacy of IL-2-based cancer vaccines remains to be verified in clinical trials." (PMID 37516849, 2023). "KKU-M055 cells inhibited IL-2 mRNA expression in Jurkat cells when combined at a ratio of 6.4:1 cancer:T cells." (PMID 37973660, 2023). "IL-2, also called Proleukin (brand name aldesleukin; Novartis), has been approved for use since 1992 and was first trialed at high doses as an anti-cancer drug." (PMID 36399073, 2023). "It not only mitigates vascular leakage, which is a crucial concern with IL-2 treatment but also maintains or enhances the anti-cancer efficacy of IL-2." (PMID 37711172, 2023). "IL-2, an approved immunotherapeutic agent for some types of cancer, is produced by activated CD8+ T lymphocytes and promotes the proliferation of T and B lymphocytes." (PMID 37649480, 2023). "For example, one study used nanoparticles to deliver interleukin-2 (IL-2), a cytokine that stimulates the immune system to attack cancer cells." (PMID 37175653, 2023). "Cancer immunotherapy has indeed revolutionized anti-cancer drugs, and IL-2 is a key immunotherapeutic agent used to stimulate the immune system to attack cancer cells." (PMID 37711172, 2023). "As we navigate this challenging yet promising landscape, the full therapeutic potential of IL-2 and IL-2R-targeted treatments in cancer immunotherapy comes into sharper focus." (PMID 37516849, 2023). "IL2 also aids the immune system by improving the ability of specific white blood cells to identify and destroy cancer cells." (PMID 36707691, 2023). "Drinking 2.5 g/kg/day of SSHT per month blocked cancer reproduction and metastasis, similar to that of IL-2 monotherapy." (PMID 37895842, 2023). "Pro-inflammatory payloads increase NK- and T-lymphocyte killing capability, but some of them (e.g., IL-2) enhance immunosuppressive properties of Tregs (regulatory T cells), mostly an unwanted effect during cancer treatment." (PMID 36839658, 2023). "Considering the ability of the immune system to recognize and destroy cancer cells, cytokines have been used to treat cancer for more than 40 years, initially, owing to the identification of IL-2." (PMID 37305384, 2023). "Although it remains to be rigorously demonstrated, we propose that the formation of better effectors is a key mechanism mediating the potent antitumor effect of IL-2-based cancer immunotherapies in preclinical mouse models." (PMID 37827864, 2023). "Initially, the earliest therapeutic applications of IL-2 were to improve immune responses in cancer patients." (PMID 37106742, 2023). "Discovering small molecules that enhance transcription factor activity (e.g., Bhlhe40) and increase soluble factors (TGF-β, IL-2, IL-15) presents a unique avenue for novel anti-cancer therapies." (PMID 37892995, 2023).